FGFR1 (fibroblast growth factor receptor 1)
Diseases named in the same sentence as FGFR1 in open-access papers (continued):
Sharing a sentence is not in itself a finding about the gene and the disease.
glioma (continued). "In glioma, FGFR abnormalities occur in approximately 8% of tumours, mainly affecting FGFR1 and FGFR3." (PMID 40467542, 2025). "FGFR1-mutant tumors have been pathologically diagnosed as DNT, rosette-forming glioneuronal tumor, low-grade glioma, and GG." (PMID 39081340, 2024). "Chromosomal translocations that fuse the tyrosine kinase domains of FGFR1 or FGFR3 and TACC1 or TACC3 have been identified in 2% to 4% of gliomas." (PMID 39087020, 2024). "FGF signaling pathway including FGFR1, FGFR4 and FGFR23 was shown to be involved in recruiting immunosuppressive cells, regulating M2 polarization of GAMs and T cell exhaustion in gliomas." (PMID 37790751, 2023). "Given the disparities between DMG_K27-BRAF/FGFR1 and classical DMG H3K27-altered, we hypothesised that DMG H3 K27-altered with MAPK-activating mutations might correspond to either (i) a new subtype of DMG or (ii) atypical aggressive MAPK-driven low-grade gliomas/glioneuronal tumours." (PMID 38066305, 2023). "It was reported that mutations of the FGFR1 kinase domain were found in human GBM tissue and the expression of FGFR1, FGFR3 and FGFR4 was increased in glioma." (PMID 37790751, 2023). "Furthermore, the cooccurrence of FGFR1 and PIK3CA hotspot mutations was observed in two tumors pathologically diagnosed as oligodendroglioma and ependymoma (P2233_109T, P7708_112T), and both were assigned to the methylation class low-grade glioma, rosette-forming glioneuronal tumors." (PMID 37221626, 2023). "Hence, we hypothesize that FGFR1-derived circRNAs may act as tumor promotors in glioma." (PMID 35059468, 2022). "Most common FGFR alterations for bladder cancer, intrahepatic cholangiocarcinoma, and glioma were FGFR3 SVs (1051/7739, 13.6%), FGFR2 REs (618/6641, 9.3%), and FGFR1 SVs (239/11 550, 2.1%), respectively." (PMID 36462464, 2022). "In gliomas, inactivation of the PI3K/AKT pathway via targeted FGFR1 inhibition increased the sensitivity of patients to temozolomide." (PMID 36676646, 2022). "There were multiple, cancer type–specific hot spots of junctions located near known oncogenes such as KIT, PDGFRA, EGFR, CDK4, MDM2 (glioma), TMPRSS2, ERG (PCa), FGFR1, and CCDN1 (BrCa)." (PMID 34891161, 2021). "The blockade of FGF signalling by various means, amongst them FGF2 antibodies, siRNAs against FGFR1, or treatment with the FGFR/VEGFR inhibitor PD173074, reveals small but significant growth inhibitory effects in glioma cell lines." (PMID 33860438, 2021). "Second, TCGA data should be provided to analyse the levels of miR‐3116 and FGFR1 in TMZ response and non‐response patients with glioma." (PMID 32181582, 2020). "In this context, it has been shown that FGFR1 expression increases as the tumor progresses from benign to malignant, whereas FGFR2 levels in human gliomas gradually diminish." (PMID 33352931, 2020). "Noteworthy, the cross-talk between FGFR1 and L1-CAM plays a role in proliferation and motility of glioma cells." (PMID 31091809, 2019). "By binding to FGFR1 the extracellular region of L1-CAM leads to receptor activation, resulting in stimulation of glioma cell proliferation and motility." (PMID 31091809, 2019). "Amplifications and mutations of PDGFRA, KIT and KDR were found in 8-15% of RMPAhigh gliomas, followed by EPHB3 (7.7%), FGFR1 (5.9%), FGFR3 (5.9%) and MET (4.1%)." (PMID 27385209, 2016). "RMPAhigh gliomas were also enriched in the expression of ERBB2, FGFR1 and MET (and its ligand HGF), DDR2 (a receptor for activated collagen fibers), as well as the WNT co-receptors ROR1 and RYK." (PMID 27385209, 2016). "RTK phospho-arrays were employed to screen activity of co-expressed receptors and our subsequent experiments demonstrated a reduction in FGFR1 and FGFR2 phosphorylation in glioma cell lines." (PMID 25314669, 2014). "Nuclear FGFR1 has been detected in both rapidly proliferating human medulloblastoma TE671 cells and slower proliferating glioma SF763 cells." (PMID 17049074, 2006).
glioma (continued). "As FGFR, and particularly FGFR1, are key regulators of GSC maintenance, radiation resistance and glioma proliferation, and because TTFields affect tumour cell proliferation, we hypothesized that FGFR might be involved in GSC response to TTFields." (PMID 40467542, 2025). "Furthermore, while less frequent, FGFR1 and FGFR3 amplifications occur in adult high-grade gliomas, contributing to receptor overexpression and ligand-independent signaling." (PMID 41567627, 2025). "In contrast to FGFR1, FGFR2 expression decreases with the glioma grade." (PMID 38255923, 2024). "FGFR1 TKDD appears to be largely absent in high-grade gliomas (HGG, but it’s been reported in rosette-forming glioneuronal tumor (RGNT), anaplastic PA, glioneuronal tumor with PA and PXA features." (PMID 38318325, 2023). "Interestingly, we observed a significantly lower expression of genes such as PDGFA, FGFR1, DLL4, and VEGFA in glioma patients with a higher TMIGD2 profile." (PMID 37261362, 2023). "Another case (#06), with a FGFR1 alteration, without 1p deletion, and a MC of diffuse pediatric high-grade glioma, RTK1 type, subtype A with a calibrated score of 0.25 was reclassified as a spinal PA by t-SNE analysis (online resource)." (PMID 36264505, 2022). "The FGFR1 level in GBM patients was more than 2-fold higher than it is a normal person, indicating a possibility of increased FGFR1-derived circRNAs in glioma." (PMID 35059468, 2022). "In response to NLGN3, multiple RTKs (VEGFR2, EGFR and FGFR1) as well as Gαi1 and Gαi3 were enriched in the endosomal fraction in P1 glioma cells, but not in Gαi1/3-silenced cells." (PMID 34373757, 2021). "Furthermore, the L1-CAM/FGFR1/Anosmin-1 complex regulates neurite branching and L1-CAM-mediated FGFR1 transactivation induces glioma cell proliferation and motility." (PMID 33352931, 2020). "In glioma, L1CAM-ECD promotes cell migration and proliferation by a mechanism that depends on αvβ3 and αvβ5 integrins and FAK, and on FGFR1 activity, suggesting that the L1CAM-ECD mediates its effect by heterophilic interactions of both integrins and the FGFR1 in these tumors." (PMID 31455004, 2019). "However, our immunofluorescence results indicated higher FGFR1 expression in pediatric LGG than HGG, which is opposite to the observations in adult gliomas supporting pediatric gliomas to be biologically distinct from adult gliomas." (PMID 30931252, 2019). "In the present study, we sought to investigate the clinical significance of FGFR3 and FGFR1 expression in two different nondiffuse gliomas: ependymomas and pilocytic astrocytomas." (PMID 28468611, 2017). "Six out of the 17 interactions have been previously linked to invasion, migration or adhesion (EPHA4-Efnb3, SEMA5A-Plxnb3, AQP4-Dag1, FGFR1-Ncam1, FGF2-Sdc2, and APP-Aplp2) whereas only 3 interactions have been previously reported in glioma (SEMA5A-Plxnb3, AQP4-Dag1, and FGF2-Sdc2)." (PMID 25365423, 2014). "Moreover, their whitish aspect suggested a deficiency in angiogenesis when using silenced cells, as previously reported for FGFR1 and FGFR2 activity in glioma cells." (PMID 23696849, 2013). "Glioma cells constitutively express high levels of nuclear FGF2 and FGFR1." (PMID 17049074, 2006). "Therefore, further restricting the FGFR1 sequencing analysis to non-diffusely growing gliomas/MNGT tumors would yield 15% FGFR1 N546/K656 mutant cases after exclusion of cases with BRAF fusion, IDH1/2, NF1 or TERT mutation." (PMID 35018490, 2022).
glioma (continued). "Recent studies have reported that chromosomal rearrangements in gliomas resulting in transcript fusion gene, such as NTRK 1/2/3 or FGFR1/2/3 fusions, could be therapeutic targets and are implicated in clinical trials (Entrectinib or Larotrectinib in pediatric patients)." (PMID 32771057, 2020). "Interestingly, in pediatric LGGs, FGFR1 levels were higher than in HGGs in 2D monolayers but in 3D environments activated FGFR1 levels were higher in the highly migratory SF188 suggesting differential roles of FGFR1 signaling among low and high grade gliomas depending on the microenvironment." (PMID 30931252, 2019). "However, gliomas typically do not express histiocytic markers and exhibit other molecular characteristics, including IDH mutations, ATRX alterations, 1p/19q co-deletions, EGFR amplification, TERT promoter mutations, H3 mutations, MYB/MYBL1 gene structural mutations, and FGFR1 mutations, etc." (PMID 40231251, 2025). "These tumors do not typically bear alterations found in pediatric gliomas (MYB, FGFR1, BRAF V600E-mutant) either." (PMID 33059718, 2020). "In this study, we found that the mutant genes in the metastatic brain tumors included ALK, MDM2, ATM, BRCA1, FGFR1, and KRAS, and there were no glioma-related mutant genes (MGMT, IDH1, IDH2, 1p/19q, BRAF, and TERT)." (PMID 32973641, 2020). "Pediatric gliomas compatible with PAAF with a very high mitotic index (in our experience, more than 10 mitoses for 10 HPFs) should benefit from DNA methylation profiling, especially in the context of nonspecific FGFR1 alterations." (PMID 31677015, 2020).
squamous cell lung carcinoma (87 papers, 2011 to 2026). A carcinoma arising from squamous bronchial epithelial cells. "FGFR1 amplification was significantly associated with shorter overall survival (OS) (58.6 months vs. 80.0 months) in patients with squamous cell lung cancer (SqCC)." (PMID 38831455, 2024). "Especially, Recent processes in molecular biology have confirmed that FGFR1 amplification is detected in approximately 20% of lung squamous cell carcinoma (SqCC) 19 and is associated with the mechanism of acquired resistance to EGFR-TKIs 26,27." (PMID 32626515, 2020). "The herein used FGFR inhibitors TKI258 and BGJ398 are already applied in clinical trials of other tumor entities, such as FGFR3 mutated bladder cancer or squamous cell lung cancer with FGFR1 amplification (e.g. NCT01004224 or NCT01831726)." (PMID 26036639, 2015). "In this study, PIK3CA mutation was relatively frequent in squamous cell lung cancer, as reported in other studies, while FGFR1 copy number gain seemed less frequent." (PMID 25348872, 2014). "FGFR1 was reported to be highly expressed in colorectal adenoma and cancer, and activating mutations and overexpression of FGFR1 have been shown to trigger the development of various cancers, e.g., breast, bladder, ovarian cancer, renal cell, and squamous cell lung cancers." (PMID 30220972, 2018). "PIK3CA mutation and FGFR1 amplification both represent potential targets for personalized squamous cell lung cancer therapy, and it may therefore be important to analyze both these gene alterations in clinical practice." (PMID 25348872, 2014). "In lung squamous cell carcinoma models, FGFR1 signaling activates the PI3K–AKT–mTOR axis, leading to HIF-1α accumulation and upregulation of GLUT1, thereby enhancing glucose uptake and glycolysis—the hallmark Warburg effect." (PMID 41514604, 2025). "A unique FGFR1 alteration involving tail-to-tail rearrangements that delete the ectodomain was identified in squamous cell lung cancer." (PMID 40393028, 2025). "Other researchers observed that an active CD44/p-AKT/AKT signaling pathway promotes resistance to FGFR1 inhibition in squamous-cell lung cancer." (PMID 40558504, 2025). "For example, the FGFR1-TACC1 fusion in glioblastoma and squamous cell lung cancer leads to FGFR1 hyperactivation, enhancing cell proliferation and inhibiting apoptosis." (PMID 40547805, 2025). "For instance, patients with squamous cell lung cancer and FGFR1 amplification demonstrate significantly reduced overall survival (OS) compared to those without amplification (58.6 months vs. 80.0 months)." (PMID 40547805, 2025). "FGFR1 amplification is relatively enriched in lung squamous cell carcinoma, with multiple reports indicating an incidence of approximately 15–20%." (PMID 41514604, 2025). "Studies have shown that FGFR1 is amplified in 19% of lung squamous cell carcinoma cases (14/73) and is more common in poorly differentiated tumors, suggesting a possible role in tumor aggressiveness." (PMID 38831455, 2024). "We first collected 52 squamous cell lung carcinomas that were positive for FGFR1 amplification, tested by FISH or Affymetrix SNP 6.0 arrays, and performed deep genomic sequencing." (PMID 37606995, 2023). "The variant NSD3 (T1232A) of the methyltransferase NSD3 caused the expression of nearby oncogenes, such as FGFR1, to be turned on by dimethylation of histone H3 lysine 36 (H3K36), which in turn drives the progression of lung squamous cell carcinoma." (PMID 36911198, 2023). "Our study did not reveal any clinical significance of FGFR1, 2, and 4 mRNA levels in terms of tumor relapse; however, the impact of FGFR1 mRNA level on squamous cell lung cancer patient survival remains controversial." (PMID 36142417, 2022). "The histone H3 lysine 36 (H3K36) methyltransferase NSD3, a neighboring gene of FGFR1, has been identified as a critical genetic driver of lung squamous cell carcinoma (LUSC)." (PMID 36291782, 2022).
squamous cell lung carcinoma (continued). "FGFR1 amplification occurs in approximately 20% of all squamous cell lung carcinomas (SCC), a predominant subtype of non-small cell lung carcinoma (NSCLC), indicating FGFR as a potential target for the new anti-cancer treatment." (PMID 34943871, 2021). "Fibroblast growh factor receptor 1 (FGFR1) is considered a potential molecular target in squamous cell lung cancer." (PMID 32207251, 2020). "Targeting fibroblast growth factor receptor 1 (FGFR1) is a potential treatment for squamous cell lung cancer (SQCLC)." (PMID 32207251, 2020). "Dovitinib is currently in phase 2 clinical trials and has demonstrated modest efficacy against lung squamous cell carcinomas harboring FGFR1 amplification." (PMID 31987043, 2020). "In a phase I study of infigratinib, amongst the 27 patients with squamous cell lung cancer harbouring a FGFR1 amplification, there were 4 partial responses (8%)." (PMID 35582593, 2019). "For lung squamous cell carcinoma, genes such as fibroblast growth factor receptor 1 to 3 (FGFR1–3), and genes in the phosphoinositide 3-kinase (PI3K) pathway seem to be more commonly mutated in lung squamous carcinoma." (PMID 31842906, 2019). "For FGFR1 amplification, clinical evidence (OncoKB level 3) exists on its actionability in lung squamous cell carcinomas." (PMID 30442178, 2018). "FGFR amplification has been reported in various cancers, including FGFR1 amplification in estrogen receptor‐positive breast cancer and squamous cell lung cancer, and FGFR2 amplification in triple negative breast cancer and gastric cancer." (PMID 29573334, 2018). "Amplification of the fibroblast growth factor receptor 1 gene (FGFR1) in NSCLC occurs in 22% of lung squamous cell carcinomas and 4% lung adenocarcinomas and correlates to poorer overall survival and shorter disease free survival." (PMID 28445992, 2017). "Several small molecules, such AZD4547 and PD173073, targeting the FGFR1 tyrosine kinase are now in clinical trials for the treatment of patients with squamous cell lung cancer and other solid malignant tumors." (PMID 29088806, 2017). "Amplification of fibroblast growth factor receptor 1 (FGFR1) is one of the most frequent targets in lung squamous cell carcinoma (SQCC)." (PMID 28558758, 2017). "Amplification of FGFR1 has been reported in 13%-22% squamous cell lung cancer, 20% breast cancer, 10%-17% head and neck squamous cell carcinoma, and 26.9% malignant peripheral nerve sheath tumor." (PMID 29088806, 2017). "FGFR1-amplification, predominantly found in squamous cell lung carcinoma, is currently an inclusion criterion in a clinical randomized phase I/II study of AZD4547 (NCT01824901)." (PMID 28368392, 2017). "FGFR1 amplification has been reported in numerous kinds of tumors, especially in squamous cell lung cancer and head and neck squamous cell carcinoma." (PMID 29088806, 2017). "FGFR1 is found to be amplified in non-small cell lung cancer, particularly in the lung squamous cell cancer (LSCC)." (PMID 26936993, 2016). "FGFR1 inhibitors are considered potential therapeutic agents in FGFR1-amplified lung squamous cell carcinoma, and early-stage clinical trials have been conducted." (PMID 26993773, 2016). "It was shown that FGFR1 amplification was significantly more prevalent among male patients (RR 2.03, 95% CI 1.57–2.63) with squamous cell lung cancer (SQCC) (RR 3.49, 95% CI 2.62–4.64) and current smokers (RR 2.63, 95% CI 1.92–3.60)." (PMID 26788508, 2015). "Perhaps more importantly, development of FGFR1 inhibitors represents a viable targeted therapy for use in squamous cell lung cancers." (PMID 26224133, 2015). "The driver genes involved in lung adenocarcinoma include KRAS, EGFR, ALK, and BRAF, and those implicated in lung squamous cell carcinoma (LSCC) include PIK3CA, FGFR1, EGFR, PDGFRA, and DDR2." (PMID 26373952, 2015).